NISCH (nischarin)
Diseases named in the same sentence as NISCH in open-access papers (continued):
Sharing a sentence is not in itself a finding about the gene and the disease.
middle ear disease (1 paper, 2017). "The discovery of the involvement of Nischarin in the development of inflammatory middle ear disease identifies a novel gene and associated pathways that are involved in OM." (PMID 28806779, 2017).
neuroblastoma (1 paper, 2013). Neuroblastoma (NB) is the most common solid, extracranial childhood tumor. "We further explored the subcellular distribution of Nischarin in rat pheochromocytoma PC-12 and mouse neuroblastoma Neuro-2a." (PMID 23342172, 2013).
otitis media (1 paper, 2024). Inflammation of the anatomical structures of the middle ear, which is most often caused by an infectious process. "A missense change L972P in the NISCH gene was previously shown to be an important factor in the development of otitis media and consequential conductive hearing loss in the mouse model." (PMID 38781180, 2024).
pancreatic ductal adenocarcinoma (1 paper, 2024). An infiltrating adenocarcinoma that arises from the epithelial cells of the pancreas. "NISCH protein levels were significantly lower in nine out of ten tumor types, all but pancreatic ductal adenocarcinoma in which it was lower, but not significantly." (PMID 38781180, 2024).
rectal cancer (1 paper, 2024). A primary or metastatic malignant neoplasm that affects the rectum. "For example, healthy rectal tissue has higher nischarin expression compared to the rest of the digestive tract, and decrease in NISCH had no prognostic value in rectal cancer." (PMID 38781180, 2024).
thymoma (1 paper, 2024). A neoplasm arising from the epithelial cells of the thymus. "NISCH was expressed at both the mRNA and protein level in all the examined healthy human tissues, and its expression was significantly decreased in most of the analyzed solid tumor types, except thymoma where it was increased." (PMID 38781180, 2024).
tumor (32 papers, 2012 to 2026). "NISCH was expressed in PDAC tumor tissue, in both the epithelial and stromal compartments of tumors, and higher NISCH expression was associated with longer patient survival." (PMID 42274623, 2026). "Further investigation into the Nischarin signaling pathways is required in order to elucidate the mechanisms underlying Nischarin-mediated inhibition of tumor cell migration and metastasis in PBC and other types of cancer." (PMID 25695373, 2015). "In this report, we found that Nischarin (NISCH), established as a tumor suppressor, is susceptible to S-glutathionylation, selectively at Cys185 located near its leucine-rich repeat (LRR) domains, which are implicated in protein-protein interactions with Rac1 and PAK1." (PMID 41213437, 2025). "Mutations in the NISCH gene may influence NISCH mRNA transcription and stability but may also have an effect on the nischarin function as a tumor suppressor." (PMID 38781180, 2024). "Association of NISCH with these interacting partners underlines its broad impact on the regulation of cell motility, cell invasion, vesicle maturation, as well as its role as a tumour suppressor." (PMID 28806779, 2017). "Given that the incidence of mutations in the NISCH gene that could possibly account for a loss of a tumor suppressor function was very low, we performed gene set enrichment analysis (GSEA) to examine the observed disparity in its prognostic value in different cancers." (PMID 38781180, 2024). "Nischarin (NISCH)/Imidazoline-1 receptor (IR-1) is a potential tumor suppressor that is involved in the regulation of cell migration, invasion, and cytoskeletal organization." (PMID 42274623, 2026). "One of the limitations of our study is that our conclusions on the role of NISCH in cancer progression rely on the bulk tumor RNA sequencing and the gene set enrichment analysis." (PMID 38781180, 2024). "Since both NISCH mRNA and protein levels showed a decrease in most human tumor tissues compared to the respective healthy tissues, we examined the possible mechanisms of NISCH downregulation in tumor types in which levels of NISCH mRNA had a prognostic value." (PMID 38781180, 2024). "We analyzed the expression of NISCH by tumor type, and it is possible that analysis by molecular subtypes would reveal further intricacies of the NISCH role in cancer progression." (PMID 38781180, 2024). "This implies that NISCH prognostic role should further be examined in each tumor type by stage, grade, and molecular subtype." (PMID 38781180, 2024). "Nischarin (Nisch) is a cytosolic scaffolding protein that harbors tumor-suppressor-like characteristics." (PMID 35163298, 2022). "Our data show the ability of the tumor suppressor, Nischarin to regulate cell attachment to the ECM." (PMID 29415725, 2018). "The tumor suppressor Nischarin interacts with a number of signaling proteins such as Integrin α5, PAK1, LIMK1, LKB1, and Rac1 to prevent cancer cell migration." (PMID 29415725, 2018). "Since this work explains the role of Nischarin in the early stages of the metastatic process, the results of our research will contribute to our understanding of the tumor microenvironment." (PMID 29415725, 2018). "Based on the data available from previous studies as well as the results of the present study, a potential model of the role of Nischarin in cell migration and tumor growth was suggested." (PMID 25695373, 2015). "Nischarin has been suggested to be involved in the inhibition of tumor cell growth via upregulation of the expression of the α5 subunit, reducing the phosphorylation of focal adhesion protein tyrosine kinase and decreasing the Rac GTP load." (PMID 25695373, 2015).
tumor (continued). "Out of the 14 TCGA cancers analyzed for the presence of NISCH promoter methylation, seven types showed significant increase in methylation levels in tumor samples with lower NISCH expression compared to the samples with higher NISCH expression: BLCA, LIHC, LUAD, KIRC, KIRP, PRAD, and TGCT." (PMID 38781180, 2024). "To examine whether the decreased NISCH mRNA expression in tumors had a prognostic value, we performed overall survival analysis of 20 tumor types." (PMID 38781180, 2024). "In line with the NISCH so far described biological roles, and regardless of the tumor type, decreased NISCH expression was associated with activation of metabolic pathways that allow increased tumor growth." (PMID 38781180, 2024). "This prompted us to question the universality of the tumor suppressor role of NISCH in cancer." (PMID 38781180, 2024). "Nischarin gene is on the 3p21.1 chromosome, location marked as a putative tumor suppressor cluster." (PMID 38781180, 2024). "We performed GSEA to look for the differences in associated gene networks in tumor types where NISCH had negative versus positive prognostic value." (PMID 38781180, 2024). "It is a downstream target of Nischarin which is a tumour suppressor." (PMID 37670049, 2023). "Low Nischarin expression levels may therefore lead to increased tumor cell proliferation and reduced cell apoptosis, resulting in carcinogenesis." (PMID 25695373, 2015). "In the rest of the tumor types NISCH could also be found in the nucleus." (PMID 38781180, 2024). "While the number of tumor samples stained in the HPA was too low for the statistical analysis with an appropriate power, it would be interesting to examine (in each tumor type individually), whether the NISCH localized in the nucleus has a specific role and an impact on tumor progression." (PMID 38781180, 2024). "In terms of the downregulation of NISCH expression, methylation of the NISCH promoter was an important factor in BLCA, LIHC, LUAD, KIRC, KIRP, PRAD, and TGCT, and shallow deletions were a common important mechanism for all the examined tumor types." (PMID 38781180, 2024). "Nevertheless, the discrepancy in the prognostic value of NISCH in SKCM, GBM and THCA may indicate sex-related differences in NISCH signaling in these tumor types and is worthy of further investigation." (PMID 38781180, 2024). "Taken together, high level of NISCH expression was not a universal marker of good prognosis in cancer patients, not even within the same tumor group (such are adenocarcinomas BRCA, COAD, PAAD, LUAD, etc.), as it was previously postulated." (PMID 38781180, 2024). "However, this does not undermine the potential of NISCH agonists for repurposing, as they are systemic drugs and would have an effect on the whole tumor tissue." (PMID 38781180, 2024).
cancer (15 papers, 2015 to 2026). A tumor composed of atypical neoplastic, often pleomorphic cells that invade other tissues. "Wnt-beta catenin, Notch and Hedgehog signaling pathways were predominantly significantly positively associated with NISCH expression in the group of cancers where NISCH was an unfavorable prognostic marker." (PMID 38781180, 2024). "Studies using cancer cells have made great progress towards understanding the molecular mechanisms underlying how Nischarin functions." (PMID 26670864, 2015). "The aim of this study was to comparatively examine the prognostic value of NISCH in solid tumors, regulation of its expression and associated signaling pathways with special emphasis on the possible differences between male and female cancer patients." (PMID 38781180, 2024). "Next, we looked to see whether there were differences in NISCH association with specific signaling pathways between cancers in which NISCH was an unfavorable and favorable prognostic marker." (PMID 38781180, 2024). "Given that NISCH expression was negatively associated with pathways that control cancer growth and progression, NISCH agonists may be of interest for repurposing in oncology." (PMID 38781180, 2024). "However, possible explanation for the differing prognostic role of NISCH in different cancer types may be attributed exactly to the NISCH association with cancer metabolism." (PMID 38781180, 2024). "Out of the three tested NISCH agonists, moxonidine, clonidine and rilmenidine, rilmenidine was the only one affecting cancer cell viability and at high doses induced cancer cell apoptosis." (PMID 42274623, 2026). "To find gene expression signatures associated with NISCH expression we defined “NISCH high” and “NISCH low” phenotype according to the NISCH mRNA levels used as a cut off in survival analysis for each cancer type." (PMID 38781180, 2024). "Here, we examined the levels of NISCH promoter methylation and the presence of mutations and copy-number alterations (CNA) in the nischarin gene in cancers in which NISCH showed to be a significant prognostic marker." (PMID 38781180, 2024). "Most of the cancers had lower NISCH levels compared to the healthy tissues, but only in some of them lower nischarin expression associated with outcome of the overall survival." (PMID 38781180, 2024). "This confirmed that NISCH was involved in several biological processes important for cancer progression." (PMID 38781180, 2024). "NISCH mRNA expression was shown to be downregulated in breast and ovarian cancer tissue compared to the adjacent healthy tissue and the lack of expression has been proposed as a marker of cancer aggressiveness." (PMID 38781180, 2024). "Even though NISCH expression was decreased across most cancer types compared to the healthy tissues, higher expression in tumors was not a universally positive prognostic marker." (PMID 38781180, 2024). "Our results lay a ground for further functional studies of the context-dependent nischarin role in cancer and investigation of the potential of NISCH agonization as a novel therapeutic approach in oncology." (PMID 38781180, 2024). "We examined NISCH mRNA and protein expression, prognostic value, transcriptional regulation, as well as its potential role in cancer progression, by examining publicly available datasets, and considering sex-related differences." (PMID 38781180, 2024). "Different from TFAP2A-AS1 and miR-3657, NISCH has been more reported in the field of functions in human cancers." (PMID 34727954, 2021). "Since Nischarin is typically down regulated in cancer cells, these results help us understand why Nischarin-expressing cells have a slow migration rate." (PMID 29415725, 2018). "Nevertheless, our findings reveal that Nischarin expression status is a significant determinant of Malat1 expression and is an important consideration in experiments investigating cancer treatments which function by altering Malat1 function or expression." (PMID 29912916, 2018).
cancer (continued). "The novel localization could also account for cancer-specific nischarin role and should be investigated in future functional studies." (PMID 38781180, 2024). "The pathways that were repeatedly associated with high NISCH expression in cancer types in which it had negative prognostic value were Wnt, Hedgehog and Notch signaling." (PMID 38781180, 2024). "NISCH prognostic value in TCGA cancers, data from the human protein atlas." (PMID 38781180, 2024). "Therefore, NISCH agonists present a great opportunity for testing as anti-cancer agents, at least in tumors in which NISCH is predicted to be a positive prognostic marker." (PMID 38781180, 2024). "Although there were pathways inversely associated with NISCH expression in male and female patients, again there were no common pathways by sex for these two types of cancer." (PMID 38781180, 2024). "To investigate the differences between tumors with the opposite prognostic value of NISCH, we examined the mutational status of NISCH gene and expression regulation mechanisms in cancer types in which the prognostic value, either negative or positive, was significant." (PMID 38781180, 2024). "Therefore, NISCH may have differing roles in cancers with different metabolic dependencies." (PMID 38781180, 2024). "Our results indicate that NISCH promoter methylation is frequent and can affect NISCH expression levels, but is not a universal mechanism for NISCH downregulation in cancer." (PMID 38781180, 2024). "Mutations in the NISCH gene were present across the length of the gene in most of the examined cancers in this study but had no significant impact on the NISCH mRNA expression level." (PMID 38781180, 2024). "Significantly enriched in the “NISCH high” phenotype in several cancer types (LIHC, OV, KIRC, LUAD, HNSC and TGCT) regardless of the NISCH prognostic role were inositol phosphate metabolism and phosphatidylinositol signaling." (PMID 38781180, 2024). "Examination of the CNA in TCGA cancers showed that NISCH amplification was very rare in tumors, and gain of additional NISCH copy was not frequent." (PMID 38781180, 2024). "Taken together, the most dominant NISCH transcript was the one coding for the full-length protein, and in the majority of the tumors most of the examined transcripts were decreased, implying that in cancer there is no NISCH isoform switching." (PMID 38781180, 2024). "This was a novel finding, as nuclear localization of NISCH in cancer cells has not been reported previously." (PMID 38781180, 2024). "Along these lines of increased production demands (under oncogenic and environmental stress during cancer progression), pathways involved in unfolded protein response, proteasome, DNA repair and reactive oxygen species pathway were all enriched in the “NISCH low” group regardless of the cancer type." (PMID 38781180, 2024).
psychiatric disorder (1 paper, 2023). A disorder characterized by behavioral and/or psychological abnormalities, often accompanied by physical symptoms. "However, cautions are also needed, as whether the aberrant dendritic spine morphogenesis caused by NISCH is sufficient to cause the cognitive symptoms in psychiatric disorders remains undetermined." (PMID 37443018, 2023). "Intriguingly, the mRNA expression of NISCH was significantly higher in the postmortem brains of patients with psychiatric disorders compared with healthy controls." (PMID 37443018, 2023).
NISCH also shares sentences with these, for which no sentence is quoted: gastric cancer (3 papers); Hypertension (3); Insulin resistance (3); Obesity (3); atherosclerosis (2); metabolic syndrome (2); pancreatic cancer (2); acute pancreatitis (1); adenocarcinoma (1); Anxiety (1); cardiac hypertrophy (1); cervical cancer (1); cholestasis (1); Cognitive impairment (1); colon cancer (1); dementia (1); diabetic neuropathy (1); HCMV infection (1); Hepatic steatosis (1); hepatoma (1); hyperlipidemia (1); infection (1); infectious disease (1); intrahepatic cholangiocarcinoma (1); invasive carcinoma (1); invasive ductal carcinoma (1); leukemia (1); major depression (1); neuropathy (1); obstructive uropathy (1).
A further 9 diseases each share a sentence with NISCH in 1 paper.